AGO1 (argonaute RISC component 1)
Diseases named in the same sentence as AGO1 in open-access papers (continued):
Sharing a sentence is not in itself a finding about the gene and the disease.
autism spectrum disorder (3 papers, 2020 to 2025). A spectrum of developmental disorders that includes autism, and Asperger syndrome. "Recent SFARI study has identified missense mutations in miRISC proteins AGO1, TNRC6B, and CNOT3 among patients diagnosed with Autism Spectrum Disorders Patients with microdeletions of chromosomal region 1p34.3 encompassing the AGO1 and AGO3 genes also show several neurodevelopmental defects." (PMID 32118035, 2020).
melanoma (3 papers, 2014 to 2021). A malignant, usually aggressive tumor composed of atypical, neoplastic melanocytes. "The melanoma cell lines displayed AGO distributions in percent of 40% to 50% AGO1, 26% to 49% AGO2, 7% to 20% AGO3 and 4% to 11% AGO4." (PMID 27518285, 2016). "Interestingly, we observed in melanoma cell lines lower concentrations of all four AGO proteins (5 to 20 fmol peptide of AGO1-4 per mg total protein) than in non-melanoma cell lines." (PMID 27518285, 2016). "Next, we determined the mRNA expression of AGO1, AGO2, AGO3 and AGO4 in different melanoma cell lines derived from primary tumors and metastases and in non-melanoma tumor cell lines." (PMID 27518285, 2016). "Among the non-melanoma cell lines, the lowest AGO concentration (34 fmol peptide of AGO1-4 per mg total protein) was found in HepG2 cells." (PMID 27518285, 2016).
renal cell carcinoma (3 papers, 2015 to 2022). "In addition, associations between polymorphisms in the XPO5 and AGO1 genes and renal cell carcinoma risk have been reported." (PMID 26147304, 2015). "The miR-153/AGO1 axis induces progression of renal cell carcinoma through activating PI3K/Akt signaling pathway." (PMID 36158686, 2022). "Also, the expression of Argonaute RISC catalytic component 1 (AGO1), a miRNA processing protein in RISC complex, is downregulated in renal cell carcinoma due to upregulation of miR-153." (PMID 36158686, 2022).
autism (2 papers, 2021 to 2025). Persistent deficits in social interaction and communication and interaction as well as a markedly restricted repertoire of activity and interest as well as repetitive patterns of behavior. "TNRC6B, PTEN, AGO1, SKI, and SMAD4 were the most frequent targets, and miR-92a-3p had the most target autism risk genes." (PMID 34744804, 2021).
autoimmune disease (2 papers, 2022 to 2024). A disorder resulting from loss of function or tissue destruction of an organ or multiple organs, arising from humoral or cellular immune responses of the individual to their own tissue constituents. "Here, we established a simple and conformation-sensitive ELISA with the aim to distinguish between AGO1 Abs against conformational epitopes and non-conformational epitopes and to reveal further characteristics of AGO1 antibodies in NP and autoimmune disease (AID)." (PMID 36341350, 2022). "While AGO2 has been described as the targeted antigen in autoimmune disease (AID)-related studies, we found both AGO1 and AGO2 to be targeted." (PMID 36341350, 2022). "AGO1- and AGO2-Abs mediate more serious autoimmune diseases." (PMID 38887290, 2024).
bladder cancer (2 papers, 2018 to 2024). "The results of GSEA revealed that AGO1 was positively correlated with focal adhesion, gap junction, and bladder cancer, but negatively correlated with antigen processing and presentation, glutathione metabolism, and lysosome." (PMID 38478802, 2024). "The association of AGO1 with AGO2 and Drosha according to our McNemar test hints at similar processes and changes of miRNA machinery in bladder cancer, although AGO2 and Drosha were different." (PMID 29857476, 2018). "The upregulation of the targets and differentiation of NMIBC and MIBC cases could improve diagnostics; additionally, AGO1 seems to hold prognostic potential for bladder cancer." (PMID 29857476, 2018). "In order to assess the clinical relevance of AGO1, AGO2 and Drosha as prognostic markers in bladder cancer patients, the Kaplan–Meier analyses of dichotomized immunoreactivity data were conducted." (PMID 29857476, 2018). "In our study, the altered expressions of AGO1, AGO2, and Drosha were investigated immunohistochemically in bladder cancer to evaluate their diagnostic and prognostic potential in non-invasive and invasive bladder carcinoma." (PMID 29857476, 2018). "With regard to bladder carcinoma, previous studies have described the overexpression of Drosha, AGO1 and AGO2 compared to non-malignant bladder tissue, which we could attribute to NMIBC." (PMID 29857476, 2018).
endothelial dysfunction (2 papers, 2021 to 2025). In vascular diseases, endothelial dysfunction is a systemic pathological state of the endothelium (the inner lining of blood vessels) and can be broadly defined as an imbalance between vasodilating and vasoconstricting substances produced by (or acting on) the endothelium. "Our findings suggest that AGO2 and AGO4 are involved in inducing endothelial dysfunction in KD, but AGO1 and AGO3 are not." (PMID 39857904, 2025). "AGO2 and AGO4 are likely to participate in the endothelial dysfunction of children with KD, with AGO4 potentially playing a key role, while AGO1 and AGO3 appear not to participate." (PMID 39857904, 2025).
fungal infection (2 papers, 2022 to 2025). "AGO1 knockout mutants exhibited reduced disease symptoms and lowered fungal biomass, whereas wild‐type and miR168b mutants showed greater susceptibility, highlighting the role of the miR168‐AGO1 module in promoting fungal infection." (PMID 39981727, 2025).
ischemic stroke (2 papers, 2020 to 2021). A stroke disorder caused by obstruction of blood flow to the brain, due to thrombotic (local blood clot formation) or embolic (due to a blood clot or other material traveling from another site) event. "Using the miRNA–mRNA interaction pairs, two target genes (specificity protein 1 (SP1) and Argonaute 1 (AGO1)) were speculated to be the primary genes of ischemic stroke." (PMID 32744319, 2020). "From the miRNA–mRNA regulatory network, two target genes (SP1 and AGO1) are speculated to be the primary genes of ischemic stroke." (PMID 32744319, 2020).
leprosy (2 papers, 2022 to 2023). Leprosy is a chronic infectious disease affecting primarily the skin and peripheral nervous system. "Comparing genotypes of patients grouped according to MB clinical form with the control group, SNPs rs639174 (DROSHA), rs636832 (AGO1) and rs4143815 (miR570) were associated with a reduced risk of MB leprosy using a dominant model." (PMID 38116294, 2023). "The genetic variant rs636832 (AGO1) was associated with protection against the development of MB leprosy." (PMID 36142557, 2022). "SNPs rs639174 (DROSHA) and rs636832 (AGO1) were also associated with decreased risk of leprosy in the dominant model (p = 0.02; OR = 0.45; 95%CI = 0.23–0.89 and p = 0.01; OR = 0.45; 95%CI = 0.23–0.89, respectively)." (PMID 36142557, 2022). "This study investigated the association of twenty-five genetic variants in miRNAs and miRNA machinery-related genes (DROSHA and AGO1) with leprosy susceptibility in a population from the Amazon region, northern Brazil." (PMID 36142557, 2022).
Wilms tumor (2 papers, 2010 to 2020). An embryonal neoplasm characterized by the presence of epithelial, mesenchymal, and blastema components. "Region 1p34–35 of chromosome 1, which includes AGO1, is frequently deleted in Wilms' tumours and neuro-ectodermal tumours." (PMID 32527935, 2020).
acute transverse myelitis (1 paper, 2024). Acute transverse myelitis (ATM) is an inflammatory demyelinating disorder of the spinal cord that can be either idiopathic (IATM) or secondary to a known cause (SATM). "The PPI network of Argonaute 1 (AGO1) and Acute Transverse Myelitis (ATM) were constructed." (PMID 38478802, 2024).
alcohol dependence (1 paper, 2023). Physical and psychological dependence on alcohol. "Moreover, Gedik reported a genetic association of DGCR8, AGO1, and AGO2 alleles with alcohol dependence risk." (PMID 38116240, 2023).
autoimmune thyroid disease (1 paper, 2019). Inflammatory disease of the thyroid gland due to autoimmune responses leading to lymphocytic infiltration of the gland. "Polymorphisms and expression of the AGO1 and AGO2 genes have been associated with autoimmune thyroid diseases." (PMID 31494269, 2019).
bladder tumor (1 paper, 2018). "We obtained significant differences between AGO1/AGO2 and AGO1/Drosha expression in bladder tumor tissue samples (p < 0.001)." (PMID 29857476, 2018).
Cirrhosis (1 paper, 2024). A chronic disorder of the liver in which liver tissue becomes scarred and is partially replaced by regenerative nodules and fibrotic tissue resulting in loss of liver function. "AGO2-Abs notably increased in cirrhosis, decompensation, and further in ACLF, unlike AGO1-Abs and AGO3-Abs." (PMID 39119295, 2024).
clear cell renal cell carcinoma (1 paper, 2022). "In clear cell renal cell carcinoma (ccRCC), overexpression of miR-153-5p is related to poor prognosis and promotes tumor growth and invasion via inhibition of argonaute 1 (AGO1)." (PMID 36189271, 2022).
colorectal cancer (1 paper, 2024). A primary or metastatic malignant neoplasm that affects the colon or rectum. "In humans, germline mutations in argonautes (AGO1 and AGO2) have been associated with defects in neurodevelopment, while somatic mutations in AGO2 appear to be common in gastric and colorectal cancers with high microsatellite instability." (PMID 38594249, 2024).
endometriosis (1 paper, 2023). The growth of functional endometrial tissue in anatomic sites outside the uterine body. "Our goal, therefore, was to evaluate whether the gene expressions of DROSHA, DGCR8, XPO5, DICER, and AGO1 to AGO4 are differential in MenSCs of women with endometriosis." (PMID 36983035, 2023).
head and neck squamous cell carcinoma (1 paper, 2021). A squamous cell carcinoma that arises from any of the following anatomic sites: lip and oral cavity, nasal cavity, paranasal sinuses, pharynx, larynx, and salivary glands. "AGO1 was also suggested as the biomarker of head and neck squamous cell carcinoma, when analysis of 21 tumor tissues revealed a significant upregulation of the AGO1 gene expression." (PMID 33668654, 2021).
heart failure (1 paper, 2020). Inability of the heart to pump blood at an adequate rate to meet tissue metabolic requirements. "The objective of the study was to examine the hypothesis that Ago1‐associated miRNAs may be more relevant to cardiac disease and heart failure compared with the serum." (PMID 32400052, 2020). "The differences may be due to the stage of heart failure, and our finding that miR‐21‐5p expression was elevated in the Ago1 complex, thus suggesting that this miRNA originated from the heart muscle and that a mechanism to reduce heart tissue damage is activated in our HF patients." (PMID 32400052, 2020).
Hodgkins lymphoma (1 paper, 2014). A heterogeneous group of malignant lymphoid neoplasms of B-cell origin characterized histologically by the presence of Hodgkin and Reed-Sternberg (HRS) cells in the vast majority of cases. "We analyzed the short RNAs from immunoprecipitated Ago1 and Ago2 proteins isolated from L591cells derived from EBV-positive Hodgkin’s lymphoma cells." (PMID 24627180, 2014).
immune deficiency (1 paper, 2017). "We first observed that RNAi knockdown of Exp5 or overexpression of Ago-1, manipulations that alter the miRNA profile of human cell lines, led to immune deficiency phenotypes." (PMID 28706002, 2017).
leukaemia (1 paper, 2021). "Hence, the biomarker potential of AGO1 and AGO2 in cancers of different origin has been extensively explored, pointing to a prognostic value of AGO proteins in solid tumors as well as leukaemia." (PMID 33668654, 2021). "Furthermore, the presence of both AGO1 and AGO2 proteins was essential for the successful induction of differentiation of leukaemia cells upon treatment with retinoic acid or 1,25-dihydroxyvitamin D3, respectively." (PMID 33668654, 2021).
lymphoma (1 paper, 2024). A malignant (clonal) proliferation of B- lymphocytes or T- lymphocytes which involves the lymph nodes, bone marrow and/or extranodal sites. "We previously identified a new class of small RNAs that specifically bind to Argonaute protein 1 (AGO1), but not AGO2, prepared from Epstein-Barr virus (EBV)-positive lymphoma cells, by small RNA sequencing." (PMID 38997262, 2024).
neuroblastoma (1 paper, 2020). Neuroblastoma (NB) is the most common solid, extracranial childhood tumor. "In neuroblastoma cell lines, AGO1 behaves as a tumour suppressor, with overexpression heightening checkpoint sensitivity and reducing cell cycle progression." (PMID 32527935, 2020).
neuropathies (1 paper, 2022). "Regarding the different disease groups among the neuropathies, 17 of 132 (12.9%) SNN patients, 4 of 116 (3.6%) CIDP patients, 3 of 81 (3.7%) SFN patients, and 4 of 105 (4.0%) ONP were AGO1-Abs-positive." (PMID 36341350, 2022).
ovarian tumour (1 paper, 2021). "PVT1 or AGO1 knockdown significantly reduced the cell viability and increased the cell apoptosis and inhibited ovarian tumour growth and proliferation." (PMID 34288373, 2021). "Collectively, these results reveal that deletion of the high level of PVT1 or AGO1 slowed the ovarian tumour growth in vivo." (PMID 34288373, 2021).
pancreatic cancer (1 paper, 2015). "The amount of Pim-3 mRNA associated with AGO1 was significantly higher in MiaPaca-2 and PCI55 pancreatic cancer cells transfected with miR-33a mimics than in parental cells or cells transfected with negative control mimics (cel-miR-239b)." (PMID 25971209, 2015).
paucibacillary leprosy (1 paper, 2022). "The SNP rs2505901 (pre-miR938) was associated with protection against the development of paucibacillary leprosy, while the SNPs rs639174 (DROSHA), rs636832 (AGO1), and rs4143815 (miR570) were associated with protection against the development of multibacillary leprosy." (PMID 36142557, 2022).
prostate adenocarcinoma (1 paper, 2013). "To determine if this feature is conserved in human cells, we examined Ago1 and Ago2 cellular distribution in the nuclear and cytosolic fractions of PC-3 (prostate adenocarcinoma) and RWPE-1 (normal prostatic epithelial) cells by immunoblot analysis." (PMID 24086155, 2013).
prostate carcinoma (1 paper, 2010). A carcinoma that arises from epithelial cells of the prostate gland. "We apply our theoretical predictions of diffusion times and lower limits for the time resolution of two components to fluorescence images in human prostate cancer cells (PC-3) transfected with fusion proteins of green fluorescence protein (GFP) and argonaute proteins (Ago1, Ago2)." (PMID 20553227, 2010).
prostate tumour (1 paper, 2023). "While for prognosis by using serum PSA levels and CDK6, TNRC6B, and AGO1 expression in prostate tumour tissue, the CART chart showed that a patient with PSA values ≤ 7.65 ng/ml, will harbour a high-risk PCa if the relative expression level of TNRC6B in PCa tissue is ≤ 5.618 (27%)." (PMID 37978493, 2023). "We checked the expression levels of CDK6, TNRC6B, AGO1, AGO3, and TNRC6A in PCa tissues, based on data from 465 prostate tumour samples obtained from TCGA-PRAD database, and stratified according to the 2014 ISUP-GG into low-risk (ISUP I and II) and high-risk (ISUP III, IV, and V)." (PMID 37978493, 2023).
skin cancer (1 paper, 2020). "Consistent with AGO1 having tumour suppressor activity, across a wide range of human cancers, large scale genomics data in cBioPortal identified AGO1 as frequently mutated or deleted in a diverse variety of tumours (e.g. reproductive, breast, intestinal, bladder, and skin cancers)." (PMID 32527935, 2020).
Urothelial Carcinomas of the Bladder (1 paper, 2018). "Despite ongoing research on bladder biomarkers, the clinicopathological impact and diagnostic function of miRNA maturation regulators Drosha and Argonaute proteins AGO1 and AGO2 in urothelial bladder carcinoma remain unclear." (PMID 29857476, 2018).
visceral leishmaniasis (1 paper, 2023). A severe form of leishmaniasis characterized by irregular bouts of fever, substantial weight loss, swelling of the spleen and liver, and anemia (which may be serious). "Of interest, among the Leishmania-upregulated Ago1-dependent proteins, Cathepsin G (CTSG), has been shown to be significantly enriched at the late chronic phase of visceral leishmaniasis in mice." (PMID 38098491, 2023).
ZIKV infection (1 paper, 2019). "Similarly, ZIKV infection in HepG2 cells led to a decrease in DGCR8, Ago1, and Ago3 expression." (PMID 30781519, 2019).